BRCA1 (BRCA1 DNA repair associated)
Diseases named in the same sentence as BRCA1 in open-access papers (continued):
Sharing a sentence is not in itself a finding about the gene and the disease.
breast cancer (continued). "For instance, miR-218 directly targets BRCA1 and that its restored expression in cisplatin resistant breast cancer cell lines sensitizes cells against the drug, affecting DNA damage." (PMID 30234015, 2018). "Mutations in the BRCA1 and BRCA2 genes remain by far the most common genetic explanation for a strong family history of breast cancer." (PMID 29039119, 2018). "BRCA1-185-del AG (c.68_69delAG) was found in the group-I (patients with age <40 years) in the breast cancer patient." (PMID 30344568, 2018). "In this context, the combined expression patterns of DDR molecules expressed in single- and double-strand breaks of DNA such as PARP1, γH2AX, and BRCA1/2 were indicators of poor prognosis of breast carcinomas and soft-tissue sarcomas." (PMID 30126387, 2018). "Taken together, these results suggest that hsa_circ_0001283 can bind to hsa-miR-146a-5p to regulate the expression of BRCA1 in breast carcinoma." (PMID 30030469, 2018). "Each candidate promoter reporter construct was co-transfected with either the WT or C61G mutant BRCA1 expression vector into human breast carcinoma MDA-MB-436 cells, followed by a luciferase reporter assay." (PMID 29757984, 2018). "Women with known BRCA1/2 mutations are strongly recommended to consider a RRSO from their early 40 s in order to reduce their increased risk of fallopian tube, ovarian and breast carcinoma." (PMID 30340058, 2018). "In this study we show that EEPD1 is required for death of BRCA1 mutant breast cancer cells that have been depleted of RAD52." (PMID 29145865, 2017). "The present study estimated the prevalence of BRCA1 and BRCA2 gene mutations in a broad Colombian population of 853 breast cancer patients." (PMID 29021639, 2017). "Increasing evidence supports the benefit of identifying BRCA1 and BRCA2 germline mutations in early breast cancer." (PMID 28120249, 2017). "This latter scenario is analogous to BRCA1 basal‐like breast cancers that actually originate from the luminal progenitors and exhibit an overall luminal‐progenitor‐like gene expression profile." (PMID 28297567, 2017). "Approximately 15% of TNBC harbor a germline mutation in BRCA1 or BRCA2; up to 80% of BRCA1 mutation-associated and 35% of BRCA2 mutation-associated breast cancer has the TNBC phenotype." (PMID 29108297, 2017). "Genetic susceptibility to breast cancer comprises inherited mutations of the BRCA1 and BRCA2 genes related to hereditary breast cancers." (PMID 28761624, 2017). "With BOADICEA the BRCA1/2 probability in the proband falls from 6.5 to 3.6% with HER2+ breast cancer in mother and rises to 12.3% with triple negative." (PMID 27796713, 2017). "Among unselected breast cancer cases, 3.3% tested positive for BRCA1/3450del4, 2.2% for BRCA1/A1708E, 1.1% for BRCA2/3034del4, and 0.4% for BRCA2/1991del4." (PMID 28680148, 2017). "All these observations clearly indicate that β-hCG induces the migratory and invasive potential by promoting the process of EMT more specifically in BRCA1 defective than BRCA1 wild-type breast cancer cells." (PMID 28869585, 2017). "BRCA1 is responsible for DNA repair and has been closely related to breast cancer, particularly in TNBCs." (PMID 29029467, 2017). "In contrast, this substitution moderately reduced proliferation of human mammary tumor HCC1937 and MDA-MB-436 cells, which carry BRCA1 mutations." (PMID 29158484, 2017). "Here, we demonstrate that β-hCG can promote tumor progression by inducing TGFβRII, specifically and selectively in BRCA1 defective breast cancer cells." (PMID 28869585, 2017). "When EEPD1 was co-depleted with RAD52 in BRCA1-/- breast cancer cells, levels of micronuclei and nuclear bridges were reduced to levels comparable to those seen in control cells." (PMID 29145865, 2017).
breast cancer (continued). "Nevertheless, further investigations are warranted since BRCA1-mutation carriers account for 10-20% of TNBC and sporadic TNBC shares many pathologic and clinical features with BRCA 1-associated breast cancer." (PMID 29088896, 2017). "The subsequent breast cancer analyses focus on the updated ER-negative breast cancer PRS for BRCA1 carriers and the updated overall breast cancer PRS for BRCA2 carriers." (PMID 28376175, 2017). "Some researchers have confirmed that some splice site variants of BRCA1 and BRCA2 can produce deleterious exonic variants which have relationship with the breast cancer families." (PMID 28881705, 2017). "Germline mutations in the tumor suppressor genes, BRCA1 and BRCA2 account for approximately 20% of cases of hereditary breast cancer cases." (PMID 27926510, 2017). "BRCA1-methylated sporadic breast cancers tend to be ‘BRCA-like’ in that they have a triple-negative phenotype." (PMID 29152070, 2017). "In the present study, we evaluated BRCA1 protein expression and cellular localization via immunohistochemical staining in a well-characterized series of breast cancer patients using MS110 monoclonal antibody that has been validated in previous studies." (PMID 28863181, 2017). "In this study, we analyzed the frequency of 7 BRCA1 and 25 BRCA2 variants in an Asian cohort of 2,110 breast cancer patients and 1,493 healthy women, in which the pathogenicity of variants is evaluated using a case-control approach." (PMID 28222693, 2017). "This study demonstrates that the synthetic lethality seen when RAD52 is depleted in BRCA1 mutant breast cancer cells depends on the HR endonuclease EEPD1." (PMID 29145865, 2017). "We are conducting a genetic study to explore BRCA1 and BRCA2 mutations among breast cancer patients diagnosed at the age of 40 years or younger." (PMID 29121898, 2017). "We define a characteristic profile for BRCAness by comparing gene expression differences between BRCA1/2 mutant familial tumors and sporadic breast cancer tumors while adjusting for relevant clinical factors." (PMID 29146938, 2017). "FOXP3 functions as a tumor suppressor in breast cancer cells but also induces expression of oncogenic miR-155 through inhibition of BRCA1, representing a heterogeneous network of the target genes affected in FOXP3-mediated tumor suppression." (PMID 28562349, 2017). "Predictive biomarkers predict the response to chemotherapy and the probability of cancer recurrence; typical examples include BRCA1 in breast cancer and K-ras in colon cancer." (PMID 29290942, 2017). "These genes include BRCA1 in breast cancer, MGMT in gliobastoma multiform (GBM), and MLH1 in colon cancer." (PMID 29038612, 2017). "We reported that alcohol increases Brf1 expression through ERα and that BRCA1 represses alcohol‐induced Brf1 expression in ER+ breast cancer lines." (PMID 28972307, 2017). "On the other hand, 5 SNVs were found in BRCA1 gene and one SNV associated with breast cancer risk in BRCA2." (PMID 28787462, 2017). "Four years later, Miki and colleagues (1994) mapped BRCA1 (Breast Cancer 1, early onset), the first breast and ovarian cancer predisposing gene." (PMID 28858227, 2017). "Associations between nuclear, cytoplasmic, and nuclear/cytoplasmic ratio of BRCA1 expression (IF staining) and clinicopathologic features in breast cancer." (PMID 28863181, 2017). "When the three groups are considered separately, the average age at diagnosis of breast cancer in the family, in the BRCA1-pathogenic, BRCA1-VUS and BRCA1-WT groups were respectively 44.1; 41.2 and 42.5 years (SD = 5.7, 9.7 and 10.7 years, respectively)." (PMID 27926510, 2017). "Particularly in breast cancer, the majority of the known susceptibility genes encode proteins with integral roles in DNA damage response (DDR), including the two major ones BRCA1 and BRCA2, and a number of others, such as PALB2, ATM and CHEK23–5." (PMID 28386063, 2017).
breast cancer (continued). "The intervention trial examined methylation level across 45 sites within a panel of 21 breast cancer-related genes (including 4 sites in BRCA1 and 1 site in BRCA2)." (PMID 28594926, 2017). "In fact, BRCA1 expression is often decreased in sporadic basal-like breast cancer, which represents around 90% of the total breast cancer cases." (PMID 28471392, 2017). "This present study has demonstrated a very low frequency of detection of BRCA1 and BRCA2 mutation carriers amongst primary screens of women with HER2 amplified breast cancers, particularly those with ER+ ve tumours." (PMID 27796713, 2017). "Similar results were obtained upon depletion of BRCA1 or BRCA2 in BT-549 breast cancer cells treated with olaparib." (PMID 28714471, 2017). "The purpose of the present project was to analyse and to characterize the metabolic profile of human breast cancer cell lines and plasma samples of TNBC from HBOC patients who were carriers and non‐carriers of germline mutations in the BRCA1 gene." (PMID 29259228, 2017). "We repeated the clonal survival experiments with a second BRCA1 mutant breast cancer cell line, SUM149PT." (PMID 29145865, 2017). "Consistently, the genomes of BRCA1-mutant breast cancer patients show frequent insertions and deletions in R-loop-rich transcription termination regions, whereas these mutations appear throughout the genome in BRCA2-mutated breast cancers." (PMID 28653981, 2017). "In two analyses restricted to BRCA1/2 carriers, higher serum OPG concentrations were associated with lower risk mutation site and lower breast cancer risk (n = 18 cases)." (PMID 28173834, 2017). "Only 32 variants (7 BRCA1 and 25 BRCA2) were present in both cases and controls and these were analyzed for association with breast cancer risk." (PMID 28222693, 2017). "When we measured HU-stressed replication fork degradation in BRCA1 mutant breast cancer cells we found that depleting RAD52 or EEPD1 led to less stressed replication fork degradation, but co-depletion of both restored degradation to control levels." (PMID 29145865, 2017). "In breast cancer, this catalogue includes CpG promoter methylation of BRCA1, RAD51C, FOXC1, RUNX3 and L3MBTL4." (PMID 28679371, 2017). "Akt1 has been reported to impair the nuclear localization and foci formation of BRCA1/Rad51 as well as HR repair in normal tissue and breast cancer cells." (PMID 29156644, 2017). "Smaller HR estimates in BRCA1 breast cancer were seen for the PRS for overall breast cancer (HR = 1.14, 95% CI = 1.11 to 1.17, P = 1.8×10−18) and ER-positive breast cancer (HR = 1.11, 95% CI = 1.08 to 1.15, P = 3.5×10−13)." (PMID 28376175, 2017). "Resveratrol prevents epigenetic silencing of BRCA-1 protein which is tumor suppressor and is involved in the repair of DNA damage through aromatic hydrocarbon receptor in human breast cancer cells." (PMID 28674526, 2017). "Females carrying mutations in genes related to DNA repair, such as BRCA1 and BRCA2, had higher risk for breast cancer." (PMID 28813639, 2017). "Our analyses indicate that the BRCAness profile defined based on familial breast cancer samples can be applied to classify BRCA1/2-mutant familial versus sporadic ovarian cancer." (PMID 29146938, 2017). "For example, breast cancer screening is recommended for BRCA1/BRCA2-positive men, beginning at age 35, and increased colon surveillance is recommended for CHEK2-positive individuals." (PMID 28008555, 2017). "Mutations in the BRCA1 and BRCA2 genes are the most common causes of hereditary breast and ovarian cancer and are associated with a lifetime risk of breast cancer of 50–85% and of ovarian cancer of 15–40%." (PMID 29292755, 2017).
breast cancer (continued). "In conclusion, an important role for the BRCA1 protein in breast cancer progression is indicated by its reduction or altered subcellular distribution in a large proportion of breast cancer patients." (PMID 28863181, 2017). "Summary of nuclear, cytoplasmic and N/C ratio of BRCA1 expression among invasive breast cancer samples (IHC staining)." (PMID 28863181, 2017). "Conversely, Akt1-KD has been reported to increase BRCA1 foci formation in MCF-7 breast cancer cells at 12 h after irradiation." (PMID 29156644, 2017). "To explore a functional link between promoter-proximal NELF-mediated Pol II pausing and BRCA1-associated R-loop accumulation, we knocked down (KD) BRCA1 and COBRA1 in T47D luminal breast cancer cells." (PMID 28649985, 2017). "Published data about referral patterns showed that the proportion of young breast cancer patients who underwent BRCA1/2 testing has been increased in the last decade particularly between 2012 and 2013." (PMID 29121898, 2017). "In another study, neither active smoking (current or ever) nor passive smoking was related to the methylation status within the promoter site of BRCA1 when measured in tumor tissue from breast cancer cases." (PMID 28594926, 2017). "Our French Canadian cohort comprised three major familial breast cancer subgroups namely BRCA1 and BRCA2 carriers as well as BRCAX individuals, i.e. non BRCA1/2 (affected and unaffected)." (PMID 29108258, 2017). "Identified risk factors for CBC include young age at first breast cancer diagnosis, breast cancer family history, mutations in BRCA1 and BRCA2 (BRCA1/2), young age at menarche, nulliparity, and obesity." (PMID 28724391, 2017). "In 2014, work by Sharma and colleagues reported the presence of BRCA1 methylation in 30% of women with sporadic breast cancer." (PMID 27926510, 2017). "In this study, we performed RNA sequencing on LCLs isolated from BRCA1/2 and BRCAX affected and unaffected individuals coming from high-risk breast cancer families in an attempt to distinguish breast cancer subgroups based on their transcriptome profile." (PMID 29108258, 2017). "Although specific mutations in BRCA1 and BRCA2 are known to be responsible for inherited susceptibility to breast cancer in families with early-onset disease, BRCA1/2 mutation carriers account for just 20% of the enhanced risk in first-degree relatives." (PMID 28569218, 2017). "The long-term aim of the present study is to explore the use of BRCA1-IRIS overexpression as a predictive biomarker for TNBCs in Egyptian breast cancer patients, and to determine its potential usefulness as a therapeutic target." (PMID 28499366, 2017). "Far less understood, however, is BRCA1 expression and subcellular distribution in breast cancer tissues." (PMID 28863181, 2017). "Literature review also recommends that high-risk genes other than BRCA1 and BRCA2 possibly enhance the risk of developing breast cancer, mainly for younger females." (PMID 28969709, 2017). "Collectively, we demonstrate that protein levels, genetic mutations, and post-translational modifications – particularly ubiquitination – can affect BRCA1’s functional state in breast cancer cells." (PMID 28262780, 2017). "In Chile, we and others have carried out mutation screening of BRCA1 and BRCA2 in hereditary breast cancer patients, leading into mutation frequencies ranging from 15% to 20%." (PMID 29088781, 2017). "Taken together, 13 out of 20 mutation carriers in this cohort actually fulfilled the Swedish BRCA testing criteria at time of breast cancer diagnosis (7 BRCA1 and 6 BRCA2)." (PMID 28120249, 2017). "It is worth mentioning that these upregulated pathways depend on two of the most studied molecules involved in breast cancer: BRCA1 and estrogen." (PMID 28496157, 2017). "BRCA1 and BRCA2 genomic insertions, deletions or single nucleotide polymorphisms are also major founder mutational events and show high-risk in many breast cancer cases." (PMID 28477017, 2017).
breast cancer (continued). "In the current study, based on our prior findings, we investigated the possible role of CTSO in drug response and breast cancer risk as a result of the regulation of ZNF423 and BRCA1." (PMID 28968398, 2017). "While rates of genetic testing among women diagnosed with breast cancer appear to be increasing 3, Black women affected with breast cancer are substantially less likely to undergo BRCA1/2 genetic testing compared to White women with the disease." (PMID 28627138, 2017). "Next, we evaluated the ability of long-term MK-0646 antibody treatment to inhibit IGF1R expression in breast cancer cells expressing a wild-type or a mutant BRCA1." (PMID 28706506, 2017). "Associations between nuclear, cytoplasmic, and nuclear/cytoplasmic ratio of BRCA1 expression (IHC staining) and clinicopathologic features in breast cancer." (PMID 28863181, 2017). "Genetic history has already provided such an example: BRCA1 and BRCA2 gene mutations significantly increase the risk of developing breast cancer; however, outcomes of carriers seem to be similar to those with sporadic breast cancer." (PMID 28830573, 2017). "Yet, the strong positive correlation between AR and BRCA1 should inspire future studies to explore AR signaling as a therapeutic target in familial breast cancers that have altered BRCA1 expression." (PMID 28863181, 2017). "Causative variants in genes such as BRCA1 and/or BRCA2 have been shown to account for hereditary nature of certain breast cancers." (PMID 29093764, 2017). "Lower nuclear to cytoplasmic ratio of BRCA1 correlated significantly with high Ki67 labeling index (p< 0.05) and family history of breast cancer (p = 0.001)." (PMID 28863181, 2017). "Breast cancer susceptibility genes BRCA1 and BRCA2 causative variant account for only 10–20% of breast cancers with a known family history." (PMID 29093764, 2017). "Pathogenic germline mutations in BRCA1 (n = 10) or BRCA2 (n = 10) were detected retrospectively in a biobank research setting, 5–7 years after breast cancer diagnosis, in 20 out of 273 breast cancer patients." (PMID 28120249, 2017). "To investigate the manner in which BRCA1 responds to oxidative stress in breast cancer cells, we employed a combination of molecular imaging and biochemical tools." (PMID 28262780, 2017). "The discovery of an N-linked glycosylation site is important in the regulation and function of BRCA1 in breast cancer, which is a potential breast cancer biomarker." (PMID 29068423, 2017). "The ER-negative PRS had the highest value of Harrell's (c = 0.58, 95% CI = 0.57 to 0.59) for breast cancer in BRCA1 carriers." (PMID 28376175, 2017). "There was general consensus that it should be applied when there was clearly no medical benefit at the time of the request for testing; for example testing a baby for Huntington disease or inherited breast cancer (e.g. BRCA1/2)." (PMID 27680566, 2017). "Several studies have focused on the methylation status of the BRCA1 gene, a key player in breast cancer including TNBC." (PMID 29138528, 2017). "Until there are licensed medications, approved by healthcare systems, for precision medicine approaches for breast cancer related to BRCA1/2 such as PARPi, these thresholds are likely to remain." (PMID 27796713, 2017). "For example, several sex-ratio genes were found to interact with brc-1 and brd-1, the orthologs of the human breast cancer genes BRCA1 and BARD1, respectively." (PMID 28506208, 2017). "The vast majority of BRCA1-driven breast cancers derive from luminal progenitor cells but the mechanisms of this lineage specificity are unclear." (PMID 28649985, 2017). "There is a very low detection rate of BRCA1 and BRCA2 mutations in women with HER2 amplified breast cancers." (PMID 27796713, 2017). "Genetic testing was performed on her two sisters and one of her sisters, diagnosed before with bilateral breast cancer, carried a BRCA1 gene with the same large genomic rearrangements." (PMID 28205045, 2017).